FOXP3 (forkhead box P3)
Diseases named in the same sentence as FOXP3 in open-access papers (continued):
Sharing a sentence is not in itself a finding about the gene and the disease.
cancer (continued). "In addition, such combined consideration of the CD8/FOXP3 ratio and PD-1 and PD-L1 expression to predict patient cluster stratification may guide anti-PD-1/PD-L1 strategies or strategies targeting Treg cells for cancer immunotherapy." (PMID 35222387, 2022). "Thus, Foxp3 activation may both suppress and stimulate cancer cell growth." (PMID 35326661, 2022). "CD8, FoxP3, and CD68 markers were evaluated by immunohistochemistry in 258 carcinoma samples and positive cells were counted in stromal and intra-tumoral compartments." (PMID 35805132, 2022). "We found that the more the cancer cells expressed SKP2, the more tumoral FOXP3 was significantly expressed." (PMID 34414959, 2021). "Our data show that the iPSC-cancer vaccine significantly decreased the CD4+CD25+FOXP3+ Treg population in TDLN and spleen, reversing the immune-suppressive microenvironment in mice injected with cancer cells." (PMID 33961792, 2021). "Several TFs have been reported to regulate immune cell infiltration in cancer, such as FOXP1, FOXP3, and c-Maf." (PMID 34489925, 2021). "For instance, regulatory T cells (T-regs or FOXP3+ T cells) are immunosuppressive subsets of CD4+ T cells, and hinder the protective immune responses in cancer-bearing hosts." (PMID 34503283, 2021). "Cancers that possess many CD4+ Treg cells, expressing the transcription factor forkhead box P3 (FOXP3), are highly immunosuppressive in nature, and a high Treg cell to CD8+ T cell ratio in the TME is associated with a poor prognosis." (PMID 34968365, 2021). "FOXP3, a member of the transcription factor family of FOX proteins, has main functions in autoimmune homeostasis and cancer development and prevention." (PMID 34768829, 2021). "Among the subtypes, EBV+ cancers differed from the other subtypes in increased lymphocyte infiltration and high CD8+/FOXP3+ ratio." (PMID 32954467, 2021). "CD3+CD4+T-bet+ T-lymphocytes were also more frequently observed in the cancer area of pCR cases (p = 0.024), as well as CD3+CD8+FOXP3+ T cells (p = 0.012)." (PMID 34715905, 2021). "Studies of infiltrating CD3, CD4, CD8, FoxP3, or CD25 positive cells and the CD4:CD8 ratio in the epithelium, stroma, or total tissue of normal, lgCIN, hgCIN, or cancer were abstracted for inclusion in the review." (PMID 33257839, 2021). "Though FOXP3 has an essential and critical role in autoimmunity, cancer development, and Treg development, with hundreds of FOXP3 target genes already identified in both cancer cells and Treg cells, the functional role of FOXP3 in regulating ATF3 is largely unknown." (PMID 34768829, 2021). "Carcinomas evade the host immune system by negatively modulating CD4+ and CD8+ T effector lymphocytes through forkhead box protein 3 (FOXP3) positive T regulatory cells’ increased activity." (PMID 34539667, 2021). "Expression of CD3, CD4, FOXP3, and PD‐L1 TPS was significantly higher in OTSCC cases relative to non‐cancer cases." (PMID 32383556, 2020). "Previous studies on GARP in the context of cancer have focused on the inhibition of the immune response through increased activation of TGF-β, especially the induction of Foxp3+ Tregs19–21." (PMID 33203838, 2020). "We first compared the immune infiltration determined by the quantitative analysis of different immune markers (CD3, CD4, CD8, PD1, PD-L1, FoxP3, CD45) between hereditary and sporadic MSI cancers." (PMID 32512823, 2020). "Mean ± SEM percentage ofCD4+CD25+FOXP3+CD45RA+ phenotype was 24.05 ±5.5%, 21.36 ± 4.7%, and 9.51 ± 3.6% respectively afterco-culturing with cancer-ASCs and normal-ASCs and inthe control group." (PMID 31721539, 2020).
cancer (continued). "After five days co-culturing naïve T cells withnormal- and cancer-ASCs, CD45RA+ T cells wereinvestigated in the population of CD4+CD25+FOXP3+and CD4+CD25-FOXP3+ cells." (PMID 31721539, 2020). "When we compared presence of the normal-ASCs and cancer-ASCs to the control group, thepercentage of CD25+FOXP3+CD73+CD39+ phenotypewas increased in both normal and cancer-ASCs.Although, this was only significant in the presenceof cancer-ASCs (P=0.005)." (PMID 31721539, 2020). "Several recent studies demonstrated the strong relationship between significant overall survival (OS) and cancer patients harboring a high number of CD8+ T cells and a low number of FoxP3+ T cells." (PMID 32245999, 2020). "The populations of CD39+CD73+CD25+FOXP3+and CD39+CD73+CD25-FOXP3+ T lymphocytes werephenotypically compared when naïve CD4+ T cellscultured with cancer-ASCs, normal-ASCs and controlgroup." (PMID 31721539, 2020). "As the infiltration of FOXP3 expressing CD4+ T cells and regulatory CD4+ T cells in TM treated tumors was decreased, this likely contributes to TM’s anti-cancer effects in vivo." (PMID 32085796, 2020). "Overall and cancer specific survival according to CRP and MMR status, stratified by infiltration of FOXP3+ cells, are illustrated in Kaplan–Meier curves." (PMID 32316975, 2020). "It is worth noting that the expression of APOA4, GCG, CYP3A4, XPNPEP2, and FOXP3, JUN were different between cancer and normal samples in TCGA database." (PMID 32547867, 2020). "In Hp+-AG-IM network the expression of APOA4, GCG, CYP3A4, XPNPEP2 and FOXP3, JUN were statistically different in the comparison of normal and cancer in TCGA database." (PMID 32547867, 2020). "Functionally, FoxP3+IL17A+ Tregs from sporadic CRC patients maintained their suppressive phenotype against CD4+ and CD8+ T cells but they were involved in cancer initiation by targeting epithelial cells in an IL17A-dependent manner." (PMID 32937953, 2020). "Patients with stage III cancer had an increase in CD8 +TEM (in 10/12) and decrease in FOXP3 +Tregs (in 10/12) following vaccination." (PMID 33177177, 2020). "This method is widely used to distinguish true Tregs from other T cell populations which transiently upregulate FOXP3 after their activation and it showed that the CD4+Foxp3hiTbethi cells found in HPV-driven cancers represent bona fide Tregs." (PMID 30658697, 2019). "The pooled hazard ratio (HR) of the overall survival (OS), disease-free survival (DFS), and cancer-specific survival (CSS) was computed to investigate the prognostic significance of CD3+, CD8+, CD45RO+, and FOXP3+ T cells." (PMID 31118034, 2019). "The counts per mm2 of CD3+, CD8+, Foxp3+, and PD-L1+ cells in CAC patients were significantly lower than those in sporadic cancer patients according to both the phenotyping method and the double positivity scoring method (all, p < 0.01)." (PMID 31048714, 2019). "Numerous human cancer cell lines, including some having a colorectal origin (e.g. HCA 2.6, HCA 3.2), have different FOXP3 expression levels which has enabled assessing its function in different in vitro conditions." (PMID 30621735, 2019). "Double staining for FOXP3 and CD4 showed that Foxp3+CD4+ cells were increased in cancer tissues of laparotomy group." (PMID 30216450, 2019). "CD4+CD25+FoxP3+ regulatory T cells are crucial to the maintenance of tolerance in normal individuals, and, so far gathered evidence indicates that presentation and progression of certain immunological disorders as well as the progression of cancer may be a function of Treg cell behavior." (PMID 31288845, 2019).
cancer (continued). "Moreover, a significant 3-fold reduced CD8:FOXP3 ratio was noted in PitNETs with a higher Ki-67, revealing that a deleterious imbalance between CD8+ and FOXP3+ T cells may lead to increased proliferation and thereby aggressiveness, as described for other cancers." (PMID 31703742, 2019). "As for the ratio of immune cells, the CD3+-to-Foxp3+ ratio and the CD3+-to-PD-L1+ ratio of CAC patients were significantly higher than those of sporadic cancer patients." (PMID 31048714, 2019). "While the Foxp3-inducing effect of the cancer ascites was mimicked by the addition of recombinant TGF-β, the ascites and TGF-β differed in that TGF-β alone induced IL-17A together with Foxp3 expression." (PMID 31310618, 2019). "FOXP3 is a member of the transcription factor family of FOX proteins and has major functions in autoimmune homeostasis and cancer development." (PMID 30011797, 2018). "EGF-like growth factor Amphiregulin (AREG), which is frequently upregulated in human cancers, reduces GSK3 activity and stabilizes Foxp3." (PMID 29102676, 2018). "Gene expression of PD-1 as well as CTLA-4, CD25, CD28, Foxp3, TGF-β and IL-10 was increased in most cancer patients compared to that in healthy adults." (PMID 28881603, 2017). "We observed that CD4+FoxP3+ Tregs in TILs expressed higher levels of Helios and the relative percentages of Tregs co-expressing FoxP3 and Helios within the TME was significantly higher than NT or peripheral blood of cancer patients." (PMID 28388539, 2017). "CD4+, CD8+, FOXP3+, CD68+, CD56+ and GZB+ cells were detected within cancer cell nests or the mesenchymal stroma." (PMID 28515351, 2017). "Ten healthy adults and 45 cancer patients were analyzed for gene expression of PD-1, CTLA-4, CD25, CD28, IL-10, TGF-β and Foxp3 in peripheral blood." (PMID 28881603, 2017). "Patients with high stromal infiltration of TILs, lower count of FOXP3+ Tregs and CD68+ Mφ in stromal site, and high expression of FOXP3 in cancer cells had longer OS." (PMID 28029650, 2017). "To compare cancer immune surveillance (represented by TILs: CD8+, CD4+, FOXP3+, CD56+, TAMs: CD68+ and GZB+ cells) in p16Ink4a -positive and negative primary tumors we analyzed mononuclear infiltrates within cancer nests only." (PMID 28515351, 2017). "Here, we show that in the context of a number of cancers, naïve CD45RA+ CD4 T cells are induced to express high levels of FOXP3, and that FOXP3 expression correlates with inhibition of T cell proliferation." (PMID 28239749, 2017). "Taken together, our results indicate that investigations of Treg levels in different cancers should consider diverse Treg-related markers such as GARP, LAP, Helios, and others and not only FoxP3 as a sole Treg-specific marker." (PMID 26885615, 2016). "Several groups have since characterized highly suppressive FoxP3+/–LAP+ Tregs in healthy donors and cancer patients." (PMID 26885615, 2016). "This study revealed the relationship between direct and indirect targets genes of Foxp3 in TSCC cells and provide molecular basis of cancer cell-derived Foxp3 function." (PMID 25779374, 2015). "Through unsupervised clustering in stage II cancers, we identified two cluster groups that are broadly defined by inflammatory or immune-related factors (CD3, CD8, COX-2 and FOXP3) and stem-like factors (CD44, LGR5, SOX2, OCT4)." (PMID 25906747, 2015). "This study reveals the relationship between direct and indirect targets genes of Foxp3 in TSCC cells and provide molecular basis of cancer cell-derived Foxp3 function." (PMID 25779374, 2015). "Integrating both subtypes and probably reflecting more comprehensive immune pattern, the ratios such as Foxp3+/CD8+ were frequently chosen as candidates for independent prognostic factors and led to positive findings in several cancers." (PMID 24276989, 2014). "Foxp3+, IL-10+, and TGF-β+ expressing cancer cells increased from early to late stages of disease compared to normal tissue." (PMID 23382847, 2013).
cancer (continued). "Next, we examined the expression of Foxp3 and immunosuppressive cytokines IL-10 and TGF-β in cancer cells." (PMID 23382847, 2013). "Specific T cell response to cancer cells and viruses is tightly regulated by regulatory CD4+ cells (Tregs) expressing fork-head box (Fox)-P3 (CD4 + CD25 + FoxP3+)." (PMID 22642942, 2012). "In the lobular histological type, there is a lower lymphocytic infiltration than in ductal cancers, particularly regarding CD4+ and FOXP3+ cells." (PMID 22471961, 2012). "Diffuse histologic-type cancers tended to have more CD8+, FOXP3+, CD57+, and DC-LAMP+ immune cells than intestinal-type cancers." (PMID 21730981, 2011). "The median proportion of Foxp3+ cells and IDO+ cells in the SLN of the cancer patients were used as cut-off levels." (PMID 19604349, 2009). "The ratio of Foxp3+ cells to CD3+ cells was higher, 0.24, among the cancer patients when compared with the ratio of 0.14 in the controls, p < 0.001." (PMID 19604349, 2009). "The curative effect of IL2 in cancer treatment is dose-dependent, but the main challenge of IL2 in terms of its use as a cancer immunotherapy was that it affects both CD8+ T cells and CD4+Foxp3+ Tregs." (PMID 41050655, 2025). "This was supported by recent profiling of the TIL single cell repertoire, which showed that FOXP3+ Tregs from cancer tissues have increased clonality compared to Tregs from normal tissues, presumably as a response to HPV-specific antigens." (PMID 41007768, 2025). "The FOXP3/CD8 ratio showed an increase in cytotoxic T-cell (CD8) expression with advancing cancer staging, histological grading, and the presence of lymph node or visceral pleural invasion." (PMID 41375087, 2025). "It was reported that in the post-prostatectomy samples patients had increased T-cells at the cancer margin as compared with the biopsy sample, but only those patients who had had prior treatment with Sipuleucel-T, which increased the number of CD4+ FOXP3—helper T-cells and cytotoxic T-cells." (PMID 40427006, 2025). "In addition to PD1-CD8+ T cells and PD1+CD8+ T cells, we analyzed regulatory T cells (FOXP3+), which contribute to the suppressive TME through their actions on CD8+ T cells, macrophages, and cancer cells." (PMID 40422184, 2025). "FoxP3 expression regulates cell differentiation in cancer cells, and its role is not restricted to Tregs." (PMID 41511327, 2025). "FoxP3 is a key transcription factor regulating the expression of several genes required for important Treg functions, such as CD25, CTLA4, CD73, and CD39, suggesting it as a potential target for cancer immunotherapy." (PMID 40034859, 2025). "In turn, Foxp3-expressing CD4+ and CD8+ Treg cells are known to inhibit the anti-cancer immunity." (PMID 39845953, 2024). "Patients with MIBC expressing forkhead box P3 (Foxp3), a transcription factor for Tregs, have a lower survival rate than patients with Foxp3-negative cancers." (PMID 38542078, 2024). "Immunohistochemical (IHC) analysis showed that Foxp3 is mainly expressed by Tregs rather than in cancer tissues." (PMID 38983267, 2024). "It has been reported that Tregs consume free fatty acids more effectively than Teffs in cancer patients due to the greater lipid uptake capacity, which is related to the specific expression of CD36, Foxp3, PD-1, TFEB, LKB1, CTLA-4, FOXO1, and co-stimulatory molecule OX40." (PMID 38644503, 2024). "Both FOXP3 and IDO1 had increased expression in cancer, further indicating T-cell suppression." (PMID 39672307, 2024). "Similarly, less activated FoxP3+ T-cells (cancer cells: p = 0.001, stroma: p = 0.020) infiltrated the tumors when COMP was expressed by both cancer cells and stroma." (PMID 38563861, 2024). "As enhanced TFH cell differentiation in a TMBHigh mouse cancer model has been shown to induce larger TLSs and superior B-cell recruitment, we next determined the density of CD4+CXCR5+PD1+FoxP3− TFH cells in HGSOC and NSCLC samples using multiplex immunofluorescence." (PMID 38514660, 2024).
cancer (continued). "At protein level, all cancer samples, were more sensitive to ASO FOXP3 than PBMC cancer samples." (PMID 39234236, 2024). "Regarding the role of FOXP3 in DNA repair, in cancer cells, the absence of FOXP3 enhances the homologous recombination (HR) pathway by activating BRCA1 expression." (PMID 39446493, 2024). "This evidence validates the previous theory regarding the protumor FOXP3 suppressing the antitumor immune cells rather than targeting the cancer cell directly." (PMID 38308298, 2024). "Interestingly, FOXP3+ T cells are usually regarded as suppressive T cells in many cancers except CRC, in which FOXP3+ T cells indicated better prognosis in some studies." (PMID 37520536, 2023). "Moreover, there were more infiltrating FOXP3+ CD4-Treg cells in GSRC than in M/PDA, and the infiltrating proportion of CD8-Teff cells in cancer tissues was lower than that in para-cancerous tissues, especially in GSRC." (PMID 37225691, 2023). "Tumors in the collagen-COMP high groups had fewer infiltrating T-cells that were CD3+ (p<0.001 for both cancer cells and stroma), CD8+ (p<0.001 cancer cells and p=0.002 stroma), and FoxP3+ (p<0.001 for both cancer cells and stroma) compared to tumors in the collagen-COMP low groups." (PMID 37207219, 2023). "Furthermore, CD68+ macrophages (p = 0.036 for margins and p < 0.001 for cancer) and FoxP3+ regulatory T lymphocytes (p < 0.001 for both) were typically less abundant in the IDC-P compared to margins and cancer." (PMID 37190147, 2023). "Other cells types such as activated CD4+CD25-T cells have also shown transient expression of FOXP3 without suppressive capabilities as well FOXP3 has also been described in certain cancers." (PMID 38077395, 2023). "previously reported that FoxP3+ Treg infiltration within p16-positive and p16-negative HNSCC tumors, was among the strongest for many cancer types, which suggests that HNSCC is characterized by both high levels of immune infiltration and high degrees of immunosuppression." (PMID 37187729, 2023). "Additionally, we also identified several genes, including FOXS1, FOXP3, and FOXD2, showed elevated expression in a variety of tumors, while FOXF1, FOXP2, and FOXO1 were downregulated in the majority of cancers." (PMID 37401400, 2023). "In distant stroma, the number of Foxp3+ cells was slightly higher in grade II carcinoma, but this result was not statistically significant." (PMID 36766393, 2023). "The fraction of PD1 expressing CD4+ T lymphocytes, CD4+Foxp3− Teff cells and CD4+Foxp3+ Tregs was not significantly different from healthy controls in cancer patients before or at various time points after brachytherapy." (PMID 35804830, 2022). "The results suggested that the combination treatment of LEM and immunotherapy might increase the expression of FOXP3, CD4+, and TGF-β and improve the quality of life and immune function of cancer patients." (PMID 36235242, 2022). "It is possible that NF-kB depletion might result in inadequate surveillance against noxious agents and cancer, but further elucidation of the safety consequences of rapamycin PFC nanoparticles in reducing splenic CD4+Foxp3+ cells might be prudent." (PMID 35159680, 2022). "At least some cancer-promoting functions of B cells can be attributed to their regulatory subsets, such as TGFβ+ CD25+ Bregs (tBregs), which support lung metastasis by inducing FoxP3+ Tregs or educating MDSCs via targeting TGFβRII5,6." (PMID 36104343, 2022).